LYVE1 (lymphatic vessel endothelial hyaluronan receptor 1)
Description:
Ligand-specific transporter trafficking between intracellular organelles (TGN) and the plasma membrane. Plays a role in autocrine regulation of cell growth mediated by growth regulators containing cell surface retention sequence binding (CRS). May act as a hyaluronan (HA) transporter, either mediating its uptake for catabolism within lymphatic endothelial cells themselves, or its transport into the lumen of afferent lymphatic vessels for subsequent re-uptake and degradation in lymph nodes. Binds to pericelluar hyaluronan matrices deposited on the surface of leukocytes and facilitates cell adhesion and migration through lymphatic endothelium.
Synonyms: LYVE-1; CRSBP-1; HAR; XLKD1
Tractability: Small molecule: a structure with a bound ligand is known. Antibody: UniProt places it where antibodies can reach, with high confidence; its Gene Ontology location is reachable by antibodies, with high confidence; UniProt predicts a signal peptide or a membrane-spanning region.
Gene: Protein-coding gene on chromosome 11 (10,556,966 to 10,611,689, reverse strand). Ensembl gene ENSG00000133800.
Subcellular location: Cell membrane
Pathways (Reactome):
Metabolism: Hyaluronan degradation; Hyaluronan metabolism
Gene Ontology:
Molecular function: cargo receptor activity; hyaluronic acid binding; protein binding; signaling receptor activity; transmembrane signaling receptor activity
Biological process: positive regulation of cellular extravasation; receptor-mediated endocytosis; anatomical structure morphogenesis; carbohydrate derivative transport; cell-matrix adhesion; response to wounding; cell adhesion; hyaluronan catabolic process
Cellular component: extracellular exosome; plasma membrane; membrane; cell periphery
Genetic constraint (gnomAD): Loss-of-function variants: 29 observed, 31.99 expected, observed/expected ratio (o/e) 0.91, 90% interval 0.67 to 1.24. The upper end of that interval is the gene's LOEUF score, 1.24, which puts it in group 5 of 6, group 1 being the genes least tolerant of losing a copy. Missense variants: 373 observed, 399.46 expected, observed/expected ratio (o/e) 0.93, 90% interval 0.86 to 1.02. Synonymous variants: 134 observed, 147.57 expected, observed/expected ratio (o/e) 0.91, 90% interval 0.79 to 1.05.
Homologues: Orthologues: chimpanzee LYVE1 (99% identical), macaque LYVE1 (94% identical), dog LYVE1 (76% identical), pig LYVE1 (72% identical), rabbit LYVE1 (70% identical), mouse Lyve1 (69% identical), guinea pig LYVE1 (61% identical), tropical clawed frog lyve1 (35% identical), zebrafish lyve1a (23% identical), zebrafish lyve1b (21% identical). Paralogues in human: CD44 (25% identical).
Diseases named in the same sentence as LYVE1 in open-access papers:
LYVE1 is named in the same sentence as 184 diseases in open-access papers, as found by Europe PMC text mining. Sharing a sentence is not in itself a finding about the gene and the disease. The quoted sentences say what the papers report.
breast cancer (42 papers, 2005 to 2025). A primary or metastatic malignant neoplasm involving the breast. "We demonstrate here an additional subset of LYVE-1+ macrophages that can be found in association with HA-rich regions associated with the mammary tumor margin." (PMID 38717149, 2024). "Macrophage subsets associated with LYVE‐1 have been identified in breast cancer in both human and mouse models with varied gene and protein expression." (PMID 38426622, 2024). "The upregulated expression of LYVE1 in tumor tissues indicates tumor-associated lymphangiogenesis and was reported to be associated with worse prognosis in breast cancer, renal cancer, and lung cancer." (PMID 31803141, 2019). "In addition to the identification of LYVE‐1+ macrophages at the mammary tumor margin, LYVE‐1+ macrophages have also been associated with lymphatic vessels." (PMID 38426622, 2024). "Thus, further investigation of the overlap between these markers and LYVE-1 was performed in both the normal mammary gland and in mammary tumors to evaluate the heterogeneity of tumor-associated LYVE-1+ macrophages." (PMID 38717149, 2024). "In addition, it has been reported that high LYVE-1-positive lymphatic vessel numbers were associated with poor prognosis in breast cancer." (PMID 36793075, 2023). "In addition, recent studies have also implicated macrophages expressing lymphatic-associated markers, including Lyve-1 and podoplanin, in mammary tumor metastasis through modulation of lymphatics." (PMID 32479261, 2020). "In addition, we will highlight two recently discovered macrophage subsets within breast cancer, lymphatic vessel endothelial hyaluronan receptor 1 (LYVE‐1)‐expressing macrophages and lipid‐associated macrophages (LAMs), and discuss emerging efforts to target these macrophages." (PMID 38426622, 2024). "In a murine breast cancer model, lymphatic vessel endothelial hyaluronan receptor-1 (LYVE-1)-expressing TAMs form coordinated multicellular nests." (PMID 41009413, 2025). "Our findings suggest that LYVE-1+ macrophages are important regulators of HA within the stromal regions of the female mammary gland and mammary tumors." (PMID 38717149, 2024). "Immunohistochemistry for LYVE-1 can be used to detect lymphatic vessel invasion, which is an effective predictor of lymphatic metastasis in breast cancer." (PMID 38791985, 2024). "For example, macrophages expressing PDPN, which is also co‐expressed with LYVE‐1 on macrophages, have been found in samples from breast cancer patients and are localized near tumor lymphatics." (PMID 38426622, 2024). "Consistent with this, we show that depletion of LYVE-1+ macrophages correlates with increased hyaluronan accumulation in both the normal mammary gland and in mammary tumors." (PMID 38717149, 2024). "We and others have identified LYVE-1+ macrophages at the tumor periphery in mouse models of melanoma and breast cancer, although the functions of these peritumoral macrophages have not been investigated." (PMID 38717149, 2024). "In summary, this study describes the localization, phenotype, and function of LYVE-1+ macrophages in the female mouse mammary gland and in mouse mammary tumors." (PMID 38717149, 2024). "For example, LYVE‐1+ macrophages were found to be localized near blood vessels in mammary tumors from a spontaneous model of mammary carcinoma, MMTV‐PyMT." (PMID 38426622, 2024). "Using the 4T1 mammary tumor model, we have previously shown that LYVE-1+ macrophages localize to the peritumoral HA-containing stroma." (PMID 38717149, 2024). "We demonstrate that LYVE-1+ macrophage depletion results in HA accumulation in both the nulliparous mammary gland and in mammary tumors, which correlates with a decrease in mammary tumor growth." (PMID 38717149, 2024). "Using both in vitro and in vivo models, we demonstrate that LYVE-1+ macrophages are associated with ECM remodeling in both the normal mammary gland and in mammary tumors." (PMID 38717149, 2024).
breast cancer (continued). "Timperi and colleagues identify an immunosuppressive LYVE-1+ macrophage subset in human patients with breast cancer, localized to the tumor stroma." (PMID 38717149, 2024). "We have previously identified LYVE‐1+ macrophages in mammary glands of mice as well as in the peritumoral stroma of murine 4T1 mammary tumors." (PMID 38426622, 2024). "Regardless of these potential caveats with the model, we felt that the significant depletion of LYVE-1+ macrophages was sufficient for further functional studies focused on their role in mammary tumor growth." (PMID 38717149, 2024). "Overexpression of LYVE1 has been suggested as a reliable marker of lymphatic metastasis in breast cancer patients." (PMID 37287543, 2023). "Collectively, the current studies align with existing evidence suggesting that LYVE1 + macrophages are responsible for HA remodeling in breast cancer." (PMID 36723776, 2023). "The dysregulation of LYVE1 closely correlated with many types of tumor, like gastric cancer, colorectal cancer, breast cancer, lung cancer and liver cancer." (PMID 33717664, 2021). "It was reported that D2-40 showed higher sensitivity in distinguishing lymphatics than PROX-1 and LYVE-1 in breast cancer tissue." (PMID 35054174, 2021). "(E) Mammary tumor sections from 4T1 tumors were immunostained for F4/80 (red) and Lyve-1 (green) (n = 4, three images/localization)." (PMID 32479261, 2020). "Human tumor tissues were surgically resected and collected from breast cancer patients for the histological examination and detection of lymphatic endothelium (indicated by LYVE1 expression) as well as MetAp2 expression." (PMID 32708166, 2020). "Given the well-established importance of macrophages in the tumor microenvironment, we assessed the localization of Lyve-1+ macrophages in mammary tumors." (PMID 32479261, 2020). "Immunohistochemical analysis of primary mammary tumours identified cell emboli within the lumen of intratumoural lymphatic vessels that stained positive for LYVE-1." (PMID 26925549, 2016). "A major challenge in the mechanistic understanding of HA in breast cancer-associated inflammation is to link HA metabolism with specific contributions of HA receptors CD44, RHAMM, and LYVE-1, which are all expressed by macrophages." (PMID 26106384, 2015). "Nevertheless, a mechanistic role for LYVE-1 in poor prognosis of breast cancer has yet to be demonstrated." (PMID 26106384, 2015). "We found that CCR7 mRNA expression in human breast cancer tissues positively correlates with the expression of lymphatic endothelial markers LYVE-1, podoplanin, Prox-1, and vascular endothelial growth factor-C (VEGF-C)." (PMID 25744065, 2015). "Using QPCR, a novel approach for quantifying lymphatic markers has been recently described in breast cancer, using LYVE-1." (PMID 18325094, 2008). "A comparison of different endothelial lymphatic markers showed that the sensitivity of D2-40 to recognize intratumoral lymphatic vessels on serial sections of breast carcinomas is higher than that of LYVE-1, podoplanin or Prox-1." (PMID 18307818, 2008). "For this reason, we analysed mRNA level of the LYVE-1 gene in the same breast cancer tissue samples in which COX-2 and VEGF-C mRNA levels were measured." (PMID 16570043, 2006). "Our study demonstrates that immunohistochemistry with LYVE-1/PCAB is a highly sensitive method for detecting tumour LV/LVI in breast cancer and LVI is a useful prognostic indicator for lymphatic tumour dissemination." (PMID 16251871, 2005). "This manuscript has focused on the utility of different LYVE-1 antibodies as routine markers for detecting and quantitating lymphatic vessels in breast cancer." (PMID 16251871, 2005). "Using a genetic mouse model of LYVE-1+ macrophage depletion, we demonstrate that loss of LYVE-1+ macrophages is associated with altered extracellular matrix remodeling in the normal mammary gland and reduced mammary tumor growth in vivo." (PMID 38717149, 2024).
breast cancer (continued). "Collectively, these studies demonstrate that macrophages expressing LYVE‐1 and associated markers (PDPN, TIM4, STAB1, and FOLR2) may have key roles in the context of breast cancer." (PMID 38426622, 2024). "Thus, further studies focused on determining the interactions between LYVE-1+ macrophages and HA in mammary tumors." (PMID 38717149, 2024). "Furthermore, perivascular LYVE-1+ macrophages have also been identified in the mouse mammary tumor virus (MMTV)-polyoma middle T (PyMT) spontaneous mammary tumor model and been shown to contribute to regulation of the angiogenic niche." (PMID 38717149, 2024). "Additionally, in comparison to Prox-1 and LYVE-1, it is more sensitive in recognizing lymphangiogenesis in breast cancer and displays the strongest immunoreactivity in both intratumoral and peritumoral LECs." (PMID 38549934, 2024). "In addition, FOLR2 + LYVE‐1 + TIM4+ macrophages have been found near blood vessels within human mammary tumors directly interacting with CD8+ T cells, resulting in a correlation between FOLR2+ macrophage count and patient survival." (PMID 38426622, 2024). "The levels of Interleukin 24 (IL-24), a cytokine that inhibits tumor progression, and its receptor, the IL-24 receptor (IL-24R), are found to be reduced in breast cancer samples and are associated with increased levels of lymph-specific markers, such as podoplanin, PROX1, and LYVE-1." (PMID 35885529, 2022). "High expression level of LYVE1 in tumor tissue can induce tumor cell proliferation, lymphangiogenesis and lymphatic metastasis, and was reported to be closely related to poor prognosis in many cancers, including lung cancer, renal cancer, and breast cancer." (PMID 34249481, 2021). "(F) Mammary tumor sections from 4T1 tumors were immunostained for Lyve-1 (red) and HABP (green)." (PMID 32479261, 2020). "In addition to localization in the mammary gland, we also found that F4/80+Lyve-1+ cells accumulate in the peritumoral stroma surrounding mammary tumors." (PMID 32479261, 2020). "Furthermore, in vitro TLR4- reprogrammed myeloid lymphatic endothelial cell progenitors (M-LECPs), generated functional cells that integrated into LYVE1+ tumor lymphatics in murine breast cancer models." (PMID 33071831, 2020). "Moreover, we show that expression of both miR526b and miR655 is positively correlated with expression of angiogenesis (CD31 and VEGFA) and lymphangiogenesis markers (VEGFC, VEGFD, and LYVE1) in human breast cancer tissue." (PMID 31277414, 2019). "Furthermore, in vitro studies suggest that HA and LYVE-1 promote adhesion of breast cancer cells to fibroblasts, predicting these interactions contribute to adhesion or dissemination of tumor cells." (PMID 26106384, 2015). "Furthermore, tumors harvested from Lyve1CreCsf1rfl/fl mice were associated with higher levels of HA than tumors harvested from control mice, suggesting that similar to the normal mammary gland, LYVE-1+ macrophages also contribute to HA modulation in mammary tumors." (PMID 38717149, 2024). "In addition, nude mice that were intradermally injected with MDA‐MB‐231 breast cancer cells and treated with the LYVE‐1 monoclonal antibody demonstrated reduced primary tumor growth with the caveat that this model lacks T cells and thus does not recapitulate the tumor immune microenvironment." (PMID 38426622, 2024). "Therefore, LYVE1 could serve as a reliable lymphatic marker for the study of lymphatic metastasis in breast cancer." (PMID 26656588, 2015). "Because we have defined a relationship between LYVE-1+ macrophages and ECM remodeling, GSEA was used to probe tissue remodeling pathways to compare macrophage clusters isolated from mammary tumors from Lyve1CreCsf1rfl/fl and control Csf1rfl/fl mice." (PMID 38717149, 2024).
breast cancer (continued). "Moreover, in immunostained paraffin tissue sections of breast cancer, a CD44-associated pericellular HA matrix has been observed on tumour emboli invading such lymphatic vessels, while in vitro cultured breast tumour lines have been reported to adhere via HA to LYVE-1 in transfected fibroblasts." (PMID 37606814, 2024). "D2-40, LYVE-1, and PROX-1 are recognized LEC markers in human breast cancer, among which D2-40 has the best performance in lymphangiogenesis assessment from the current study." (PMID 35054174, 2021). "It was found that all lymphatic endothelial markers, LYVE-1, Prox1, podoplanin, 5'-nucleotidase and VEGFR-3, were expressed in significantly higher levels in breast cancers than in normal breast tissue." (PMID 18325094, 2008). "Expression of LYVE-1, a selective marker for lymphatic endothelium, was also positively correlated with COX-2 or VEGF-C expression in breast cancer tissues." (PMID 16570043, 2006). "Using two distinct orthotopic mammary tumor models in immune competent mice, we observed a decrease in tumor growth in the absence of LYVE-1+ macrophages, and using the EO771 model, a reduction in lung colonization." (PMID 38717149, 2024). "Taken together, our findings demonstrate that LYVE-1+ macrophages contribute to ECM remodeling and represent a subset of tumor supportive macrophages that may provide a novel target for breast cancer treatment." (PMID 38717149, 2024). "In addition, M-LECPs expressing high levels of LYVE1, PDPN, PROX1 and VEGFR3 were uniquely detected in the lymph vessels of breast cancer tissue and their density correlated with the development of lymphatic metastasis in breast cancer patients." (PMID 33071831, 2020). "LYVE-1+ TAMs were located primarily in the marginal zone and not in central hypoxic regions, which has also been described in orthotopically grown mammary tumors." (PMID 29262593, 2017). "In tumors, the density of stromal LYVE-1 positive lymphatic vessels is a negative prognostic indicator in breast cancer patients with invasive ductal carcinomas." (PMID 26106384, 2015). "In this study, we used LYVE1 as the specific lymphatic markers and found that LYVE1 was expressed specifically in the lymphatic endothelial cells in breast cancer tissues without being expressed in blood vessel endothelial cells." (PMID 26656588, 2015). "HAhigh-HS-578T breast cancer cells had greater adherence to COS-7LYVE-1(+) than COS-7LYVE-1(−) cells via the interaction between HA and lymphatic endothelial cell specific hyaluronic acid receptor LYVE-1." (PMID 23717428, 2013). "In the present study, which measured LYVE-1 mRNA levels in noninflammatory breast cancer tissues as indicators of lymphangiogenesis, the location of the lymphatics remains undetermined." (PMID 16570043, 2006). "Furthermore, LYVE-1 has no variants, whereas CD44 has several variants and CD44-positive capillaries are found in various cancers, including breast cancer." (PMID 39273689, 2024). "A total of 7.5 × 104 EO771 mammary tumor cells were orthotopically implanted into the mammary fat pads of recipient C57BL/6 mice and mammary tumors were harvested at sizes of 0.5 and 1.5 cm3, representing early- and late-stage tumors, and LYVE-1+ macrophages were evaluated by flow cytometry." (PMID 38717149, 2024). "Therefore, our results support the notion that HA promotes tumor progression mediated by other receptors such as the receptor for HA-mediated motility (RHAMM), lymphatic vessel endothelial receptors (LYVE-1), and toll-like receptors 2 (TLR2) and 4 (TLR4) in canine mammary tumor." (PMID 23426189, 2013). "LYVE-1 is a highly selective marker of lymphatic endothelial cells and is not expressed by MDA-MB-231 breast cancer cells." (PMID 16570043, 2006).
breast cancer (continued). "For example, markers of myeloid lymphatic endothelial cell progenitors (M-LECPs) were found to be expressed on a portion of lymphatic vessels in breast cancer tissue, but not in normal breast tissue, and M-LECPs co-expressed high levels of PROX1, LYVE-1, podoplanin, and VEGFR-3." (PMID 35054174, 2021).